DNM1L (dynamin 1 like)
Description:
Functions in mitochondrial and peroxisomal division. Mediates membrane fission through oligomerization into membrane-associated tubular structures that wrap around the scission site to constrict and sever the mitochondrial membrane through a GTP hydrolysis-dependent mechanism. The specific recruitment at scission sites is mediated by membrane receptors like MFF, MIEF1 and MIEF2 for mitochondrial membranes. While the recruitment by the membrane receptors is GTP-dependent, the following hydrolysis of GTP induces the dissociation from the receptors and allows DNM1L filaments to curl into closed rings that are probably sufficient to sever a double membrane. Acts downstream of PINK1 to promote mitochondrial fission in a PRKN-dependent manner. Plays an important role in mitochondrial fission during mitosis. Through its function in mitochondrial division, ensures the survival of at least some types of postmitotic neurons, including Purkinje cells, by suppressing oxidative damage (By similarity). Required for normal brain development, including that of cerebellum. Facilitates developmentally regulated apoptosis during neural tube formation (By similarity). Required for a normal rate of cytochrome c release and caspase activation during apoptosis; this requirement may depend upon the cell type and the physiological apoptotic cues (By similarity). Required for formation of endocytic vesicles. Proposed to regulate synaptic vesicle membrane dynamics through association with BCL2L1 isoform Bcl-X(L) which stimulates its GTPase activity in synaptic vesicles; the function may require its recruitment by MFF to clathrin-containing vesicles. Required for programmed necrosis execution. Rhythmic control of its activity following phosphorylation at Ser-637 is essential for the circadian control of mitochondrial ATP production. [Isoform 1]: Inhibits peroxisomal division when overexpressed. [Isoform 4]: Inhibits peroxisomal division when overexpressed.
Synonyms: DVLP; Dymple; HdynIV; DLP1; DRP1; VPS1; EMPF; EMPF1; OPA5
Tractability: Small molecule: a structure with a bound ligand is known; a high-quality ligand is known. Antibody: UniProt places it where antibodies can reach, with medium confidence. PROTAC: UniProt records ubiquitination sites on it; ubiquitination databases record sites on it; its protein half-life has been measured; a small molecule that binds it is known.
Target class: Enzyme; Hydrolase
Gene: Protein-coding gene on chromosome 12 (32,679,200 to 32,745,650, forward strand). Ensembl gene ENSG00000087470.
Subcellular location: Cytoplasm, cytosol; Golgi apparatus; Endomembrane system; Mitochondrion outer membrane; Peroxisome; Membrane, clathrin-coated pit; Cytoplasmic vesicle, secretory vesicle, synaptic vesicle membrane
Subcellular location (Human Protein Atlas): Cytosol; Vesicles
Pathways (Reactome):
Programmed Cell Death: Apoptotic execution phase
Gene Ontology:
Molecular function: GTP-dependent protein binding; GTPase activity; identical protein binding; protein binding; protein homodimerization activity; small GTPase binding; ubiquitin protein ligase binding; GTPase activator activity; microtubule binding; GTP binding
Biological process: endoplasmic reticulum organization; intracellular distribution of mitochondria; mitochondrial fission; mitochondrial fragmentation involved in apoptotic process; mitochondrial membrane fission; mitochondrion organization; peroxisome fission; positive regulation of mitochondrial fission; positive regulation of neutrophil chemotaxis; positive regulation of protein secretion; protein complex oligomerization; regulation of mitophagy; heart contraction; positive regulation of secretion by cell; regulation of ATP metabolic process; regulation of mitochondrion organization; regulation of peroxisome organization
Cellular component: cytoplasm; cytosol; endomembrane system; endoplasmic reticulum; Golgi apparatus; membrane; microtubule; mitochondrial outer membrane; mitochondrion; mitochondrion-derived vesicle; perinuclear region of cytoplasm; peroxisome; protein-containing complex; endoplasmic reticulum membrane; brush border; clathrin-coated pit; synaptic vesicle membrane
Genetic constraint (gnomAD): Loss-of-function variants: 31 observed, 82.61 expected, observed/expected ratio (o/e) 0.38, 90% interval 0.28 to 0.51. The upper end of that interval is the gene's LOEUF score, 0.51, which puts it in group 2 of 6, group 1 being the genes least tolerant of losing a copy. Missense variants: 446 observed, 878.54 expected, observed/expected ratio (o/e) 0.51, 90% interval 0.47 to 0.55. Synonymous variants: 272 observed, 308.1 expected, observed/expected ratio (o/e) 0.88, 90% interval 0.8 to 0.98.
Gene-disease validity (ClinGen):
ClinGen rates the evidence that DNM1L causes each of these diseases.
encephalopathy due to mitochondrial and peroxisomal fission defect (autosomal dominant): Definitive. A rare mitochondrial disease characterized by a variable phenotype comprising delayed psychomotor development or neurodevelopmental regression, hypotonia, seizures, microcephaly, optic atrophy, pyramidal signs, and peripheral neuropathy, among others.
Leigh syndrome (autosomal dominant; autosomal recessive): Limited. A progressive neurological disease defined by specific neuropathological features associating brainstem and basal ganglia lesions.
Homologues: Orthologues: chimpanzee DNM1L (100% identical), macaque DNM1L (100% identical), dog DNM1L (99% identical), guinea pig DNM1L (99% identical), rat Dnm1l (99% identical), pig DNM1L (98% identical), mouse Dnm1l (95% identical), rabbit DNM1L (90% identical), zebrafish dnm1l (86% identical), tropical clawed frog dnm1l (74% identical). Paralogues in human: DNM2 (42% identical), DNM1 (42% identical), DNM3 (41% identical), MX1 (25% identical), MX2 (25% identical), OPA1 (20% identical).
Diseases named in the same sentence as DNM1L in open-access papers:
DNM1L is named in the same sentence as 161 diseases in open-access papers, as found by Europe PMC text mining. Sharing a sentence is not in itself a finding about the gene and the disease. The quoted sentences say what the papers report.
breast carcinoma (23 papers, 2013 to 2025). "Specifically, amplifications of OPA1, MFN1, and DNM1L (encoding Drp1) were found in more than 5% of high-grade serous ovarian cancers (HGSOC), breast carcinomas, and lung adenocarcinomas." (PMID 40724998, 2025). "Studies have shown that DNM1L expression is elevated in lung adenocarcinoma, hepatocellular carcinoma, breast cancer, and head and neck cancer, and it is correlated with poor patient prognosis." (PMID 39507763, 2024). "This inhibition of autophagy/mitophagy by liensinine led to the sensitization of doxorubicin-induced cell death of breast cancer cells via increased dynamin-1-like protein (DNM1L) dephosphorylation and translocation to mitochondria and increased mitochondrial fission." (PMID 35158798, 2022). "In addition, through DNM1L-mediated mitochondrial fusion, mitophagy can enhance the sensitivity of breast cancer cells to liensinine." (PMID 32587855, 2020). "Liensinine, a new inhibitor of autophagy and/or mitophagy, could enhance the sensitivity of breast cancer cells to chemotherapy via mitochondrial fission mediated by DNM1L." (PMID 32587855, 2020). "Recent studies show that DNM1L could repress apoptosis of cancer cells and promote migration and invasion in breast cancer." (PMID 29137373, 2017). "In two luminal breast cancer lines (T47D and ZR751) with DNM1L knockdown, we found that variations in the residual DNM1L protein among replicates correlated positively with the abundance of CDK4 but not a housekeeping control, as predicted by the positive LASSO dependency." (PMID 39333715, 2024). "Interestingly, heightened Drp-1/DNM1L expression in cancerous and metastatic tissue compared to normal tissue does not appear to be breast cancer specific." (PMID 38489056, 2024). "Liensinine affects the dephosphorylation and mitochondrial metastasis of DNM1L, which inhibits the recruitment of RAB7A to lysosomes, thereby blocking autophagosome–lysosome fusion and enhancing doxorubicin-mediated apoptosis, ultimately reducing the activity of breast cancer cells." (PMID 34065886, 2021).
Encephalopathy (18 papers, 2018 to 2025). Encephalopathy is a term that means brain disease, damage, or malfunction. "Heterozygous, mostly de novo, pathogenic variants in DNM1L, encoding dynamin-like protein-1 (DRP1), cause a lethal encephalopathy due to defective mitochondrial and peroxisomal fission 1 (EMPF1, OMIM #614388)." (PMID 39859560, 2025). "Previous cases reported a frequent association between DNM1L mutations and encephalopathy with recurrent status epilepticus (focal or generalized) followed by cognitive regression and death in early childhood." (PMID 39063023, 2024). "DRP1 impairment causes two neurological diseases associated with pathogenic variants in DNM1L (MIM*603,850), including encephalopathy due to defective mitochondrial and peroxisomal fission-1 (EMPF1, MIM #614,388) and optic atrophy 5 (MIM#610,708)." (PMID 38341530, 2024). "Mutations in the DNM1L gene encoding Drp1 result in severe and predominantly lethal encephalopathy known as EMPF1 (MIM#614388)." (PMID 39191736, 2024). "The disease associated with mutations in DNM1L is known as encephalopathy due to defective mitochondrial and peroxisomal fission-1 (EMPF1; OMIM 614388)." (PMID 36763487, 2023). "Patients with de novo heterozygous missense mutations in DNM1L present with encephalopathy due to defective mitochondrial and peroxisomal fission (EMPF1) – a devastating neurodevelopmental disease with no effective treatment." (PMID 36763487, 2023). "Monoallelic and biallelic pathogenic variants in DNM1L, which encodes DRP1, causes encephalopathy due to defective mitochondrial and peroxisomal fission 1 (EMPF1)." (PMID 35736332, 2022). "Whole-exome sequencing revealed a heterozygous de novo variant in the GTPase domain of DNM1L [NM_001278464.1: c.176C>A p.(Thr59Asn)] making her the oldest patient suffering from encephalopathy due to defective mitochondrial and peroxisomal fission-1." (PMID 36212643, 2022). "While epilepsy and encephalopathy are common among patients with pathogenic variants in DNM1L, there are also reports of peripheral neuropathy in some patients with heterozygous mutations in the GTPase domains." (PMID 33810506, 2021). "Pathological variants in DNM1L induce a disorder known as Encephalopathy due to Defective Mitochondrial and Peroxisomal Fission 1 first described in 2007 in a newborn with microcephaly and optic atrophy." (PMID 33426505, 2020). "Mutations in the DNM1L gene cause encephalopathy which is lethal due to defective mitochondrial and peroxisomal fission (type 1) (MIM 614388, autosomal dominant)." (PMID 29344903, 2018). "Mutations in MFF lead to a similar phenotype to DNM1L mutations (encephalopathy, lethal, due to defective mitochondrial peroxisomal fission 2, autosomal recessive)." (PMID 29344903, 2018). "DNM1L-related phenotype ranges from non-syndromic optic atrophy to infantile/early childhood onset lethal encephalopathy through an ‘intermediate EMPF1’." (PMID 39859560, 2025). "DNM1L-related phenotypes include static or (early) lethal encephalopathy and neurodevelopmental disorders." (PMID 39859560, 2025). "Pathogenic variants in DNM1L, encoding dynamin-like protein-1 (DRP1), cause a lethal encephalopathy." (PMID 39859560, 2025).
optic atrophy (12 papers, 2012 to 2025). A disorder characterized by loss of optic nerve fibers. "Bioinformatics analysis, coupled with phenotypic filtering using the HPO terms “Optic atrophy” (HP:0000648) and “Gait disturbance” (HP:0001288), led to prioritizing a variant in the DNM1L gene (NM_012062.5)." (PMID 41008537, 2025). "Particularly, pathogenic variants in the gene DNM1L can lead to a broad range of clinical phenotypes, ranging from isolated optic atrophy to severe neurological conditions." (PMID 41008537, 2025). "From a genetic point of view, only two DNM1L variants in the GTPase domain have been associated in three unrelated families with isolated optic atrophy reported as OPA5 mutants." (PMID 39859560, 2025). "Likewise, de novo heterozygous mutations can affect DNM1L, encoding a protein with a major role in mitochondrial fission, usually associated with severe, infantile encephalopathy, whereas transmissible, recessive DNM1L mutations cause a form of optic atrophy (OA5) (OMIM *603850)." (PMID 35203288, 2022). "Heterozygous or de novo mutations in the dnm1l gene, coding for DRP1 protein, have been shown to cause microcephaly, optic atrophy, hypoplasia, epileptic encephalopathy, and neurodevelopment delay." (PMID 39336173, 2024).
epilepsy (11 papers, 2016 to 2025). A brain disorder characterized by episodes of abnormally increased neuronal discharge resulting in transient episodes of sensory or motor neurological dysfunction, or psychic dysfunction. "In humans, DNM1L variants can cause lethal neonatal-onset encephalopathy or diverse degrees of cognitive impairment and epilepsy, indicating their essential role in the nervous system." (PMID 36908591, 2023). "Further analysis of the data also revealed a heterozygous missense variant in DNM1L, a gene previously implicated in an autosomal dominant encephalopathy, epilepsy, and global developmental delay and confirmed by Sanger sequencing to be a de novo variant not present in parental genomes." (PMID 31475481, 2019). "The patients might have severe psychomotor retardation, dystonia, and epilepsy, indicating an essential role of DNM1L in the nervous system." (PMID 36908591, 2023).
Alzheimer disease (9 papers, 2016 to 2025). A progressive, neurodegenerative disease characterized by loss of function and death of nerve cells in several areas of the brain leading to loss of cognitive function such as memory and language. "The abnormal activation of DNM1L has been reported in Alzheimer’s disease and Huntington’s disease, both of which promoted mitochondrial fission and damaged neurons." (PMID 33424801, 2020).
diabetes (9 papers, 2017 to 2022). "Mitophagy is also well implicated in Alzheimer's disease, Parkinson's disease, cerebral ischemia, multiple sclerosis, diabetes, and obesity with involvements of Dynamin-1-like protein (Drp1)." (PMID 35095749, 2021).
dilated cardiomyopathy (9 papers, 2020 to 2025). Cardiomyopathy which is characterized by dilation and contractile dysfunction of the left and right ventricles. "Interestingly, a mouse model of dilated cardiomyopathy is heterozygous for the DNM1L pathogenic variant in the MD." (PMID 39859560, 2025). "Notably, muscle-specific Drp1 knockout (Drp1-KO) mice showed neonatal lethality due to dilated cardiomyopathy, and other studies reported association between DNM1L and cardiac involvement in mouse models." (PMID 39063023, 2024). "Cardiac involvement in patients with DNM1L-related mitochondrial disease has previously been postulated because a C452F substitution in mouse DRP1 (position p.Cys446Phe in human DRP1 NP_036192.2) was shown to cause dilated cardiomyopathy." (PMID 35914810, 2022). "In a conditional cardiac KO Dnm1l mice model, the Dnm1l downregulation induced at the age of 15 weeks provoked a lethal dilated cardiomyopathy 8 weeks later through altered mitochondrial respiration." (PMID 33765018, 2021).
Parkinson disease (9 papers, 2013 to 2024). A progressive degenerative disorder of the central nervous system characterized by loss of dopamine producing neurons in the substantia nigra and the presence of Lewy bodies in the substantia nigra and locus coeruleus. "DNM1L is implicated in several neuronal diseases, such as Alzheimer’s, Parkinson’s, Huntington’s, and amyotrophic lateral sclerosis." (PMID 23977156, 2013). "Analysis of DNM1L genes rare variant burden in Parkinson's disease." (PMID 36908591, 2023). "Moreover, a loss of dynamin-1-like protein (DRP1), a key protein in the fission machinery within dopaminergic neurons, causes a Parkinson’s like phenotype in affected mice due to degeneration of SN neurons." (PMID 31083583, 2019). "DNM1L is also closely related to the metabolism of exogenous substances and drug metabolism of cytochrome P450 (CYP450), and mitochondria-targeted cytochrome P450 2D6 (CYP2D6) can efficiently catalyze the MPTP compounds that may induce Parkinson’s disease in humans." (PMID 39507763, 2024).
developmental delay (8 papers, 2019 to 2025). "Conversely, the p.Arg710Gly and p.Tyr691Cys variants were linked to the core features of DNM1l-associated disorders, including dystonia, developmental delay, and seizures." (PMID 41244260, 2025). "De novo heterozygous pathogenic variants in DNM1L have been previously reported to be associated with neonatal or infantile-onset encephalopathy characterized by hypotonia, developmental delay and refractory epilepsy." (PMID 39063023, 2024). "De novo heterozygous pathogenic variants in the DNM1L gene have been previously reported to be associated with neonatal or infantile-onset encephalopathy characterized by hypotonia, developmental delay and refractory epilepsy." (PMID 39063023, 2024). "We describe a 4.5-year-old male child harboring a novel de novo mutation in DNM1L presenting a phenotype of developmental delay, ataxia, and peripheral neuropathy." (PMID 33718295, 2021). "Defects in human mitochondrial dynamics caused by de novo monoallelic or biallelic pathogenic DNM1L variants are often associated with developmental delay, hypotonia and neurological disorders, including encephalopathy, refractory seizures, and/or autosomal dominant optic atrophy." (PMID 35914810, 2022). "EMPF1, caused by monoallelic or biallelic pathogenic DNM1L variants, is frequently associated with developmental delay, hypotonia, refractory epilepsy, and even death." (PMID 38341530, 2024). "Global Dnm1l KO embryos are significantly smaller than wild type littermates, indicative of developmental delay, while cerebellum-specific KOs, which survive marginally longer until ~36 h after birth, show further defects in cerebellar development." (PMID 35741050, 2022). "The human CDK19 patients show some similar but milder phenotypes, including developmental delay, seizure, and hypotonia, suggesting that the function of DNM1L is not fully dependent on Pink1 and CDK19." (PMID 38637532, 2024).
heart failure (7 papers, 2010 to 2025). Inability of the heart to pump blood at an adequate rate to meet tissue metabolic requirements. "Recently it has been reported that mitochondria are smaller in failing hearts and DNM1L protein levels were increased in DCM heart samples but until now, there has been no direct evidence that genes involved in regulating mitochondrial dynamics might be involved in heart failure." (PMID 20585624, 2010).
Obesity (7 papers, 2021 to 2024). Accumulation of substantial excess body fat. "Moreover, bioinformatic analysis of published microarray data (Gene Expression Omnibus (GEO) GSE70353) from 770 human males further confirmed that DNM1L is associated with obesity." (PMID 38286821, 2024). "Adipose tissue expression of the human homolog of Drp1, DNM1L, is positively correlated with obesity and insulin resistance." (PMID 38286821, 2024). "Increased expression levels of the DNM1L proteins may correlate with the degree of weight gain, and is closely related to the development of obesity." (PMID 37662987, 2023). "In human subcutaneous WAT, DNM1L (encoding human Drp1 protein) expression was positively correlated with BMI and HOMA, and its expression was significantly upregulated in obese subjects, indicating that increased expression of DNM1L may contribute to mitochondrial dysfunction in obesity." (PMID 37398165, 2023). "The DNM1L, MFN2, and TFAM gene expression levels in GO and SAT responsible for regulating mitochondrial dynamics were increased in obese patients without T2DM, and DNM1L and TFAM proteins production were unbalanced in patients with obesity and T2DM." (PMID 34572446, 2021).